ANGPTL4 (angiopoietin like 4)
Diseases named in the same sentence as ANGPTL4 in open-access papers (continued):
Sharing a sentence is not in itself a finding about the gene and the disease.
coronary atherosclerosis (6 papers, 2018 to 2024). Atherosclerosis of the coronary vasculature. "Sun and colleagues (2021) showed that circulating levels of ANGPTL3 and ANGPTL4 were independent risk factors for coronary atherosclerosis." (PMID 39728292, 2024). "To answer this question, we performed a study of ANGPTL3 and ANGPTL4 in a cohort of patients with angina to clarify the associations of these proteins with coronary atherosclerosis severity." (PMID 34742313, 2021). "ANGPTL3 and ANGPTL4 were determined to be independent risk factors for coronary atherosclerosis with odds ratios (ORs) of 0.189 (95% CI 0.097-0.368, P < 0.001) and 3.625 (95% CI 1.873-7.016, P < 0.001), respectively." (PMID 34742313, 2021). "Angiopoietin-like 4 (ANGPTL4) is an endogenous inhibitor of lipoprotein lipase that modulates lipid levels, coronary atherosclerosis risk, and nutrient partitioning." (PMID 29899519, 2018). "Increased ANGPTL3 or decreased ANGPTL4 shows an association with coronary atherosclerosis and, may become a predictor of coronary atherosclerosis in the future." (PMID 34742313, 2021). "This study comprehensively investigated the association between plasma ANGPTL3 or ANGPTL4 levels and coronary atherosclerosis severity, included the comparisons among different groups according to the degree of coronary stenosis and numbers of involved vessels." (PMID 34742313, 2021). "Finally, considering the results of the study, they do not explain the causal relationships, only showing an association between ANGPTL3, ANGPTL4 and coronary atherosclerosis severity." (PMID 34742313, 2021). "However, in the multivariable logistic regression analysis, ANGPTL3 and ANGPTL4 were determined to be independent risk factors for coronary atherosclerosis with odds ratios (ORs) of 0.189 (95% CI 0.097-0.368, P < 0.001) and 3.625 (95% CI 1.873-7.016, P < 0.001) respectively." (PMID 34742313, 2021). "The results showed that ANGPTL3 was significantly increased and ANGPTL4 was decreased in the coronary atherosclerosis group." (PMID 34742313, 2021). "The optimal ANGPTL4 cutoff point for coronary atherosclerosis was 497.5 ng/mL with a sensitivity of 63.9% and specificity of 74.5%." (PMID 34742313, 2021). "Interestingly, PLG, ITIH4, FN1, and ANGPTL4, all protective against MI, were also inferred to be protective against coronary atherosclerosis." (PMID 40027362, 2024). "ANGPTL3 or ANGPTL4 may become a convenient biomarker for screening and predicting coronary atherosclerosis in the future." (PMID 34742313, 2021). "Increased ANGPTL3 and decreased ANGPTL4 exhibit an essential association with coronary atherosclerosis severity regardless of their lipid levels." (PMID 34742313, 2021). "Both ANGPTL3 and ANGPTL4 were significantly related to coronary atherosclerosis." (PMID 34742313, 2021). "On the contrary, a plasma concentration of ANGPTL4 below 497.5 ng/mL could be used to predict the occurrence of coronary atherosclerosis (sensitivity = 63.9%, specificity = 74.5%)." (PMID 34742313, 2021). "Does ANGPTL3 or ANGPTL4 represent a better predictive indicator for coronary atherosclerosis?" (PMID 34742313, 2021). "ANGPTL3 could play a possible role in the development of coronary atherosclerosis, and ANGPTL4 may be a protective factor against atherosclerotic plagues." (PMID 34742313, 2021). "Moreover, ANGPTL3 and ANGPTL4 may act as independent predictors of coronary atherosclerosis." (PMID 34742313, 2021).
glioblastoma (6 papers, 2009 to 2025). The most malignant astrocytic tumor (WHO grade IV). "STAT3 and ANGPTL4 (encode Angiopoietin-like 4) are directly correlated in glioblastoma patients and increased expression of these genes results in poor survival." (PMID 31534498, 2019). "Therefore, Ad-GSCs and Sp-GSCs produced histologically identical tumors with different gene expression patterns, and a STAT3/ANGPTL4 pathway is identified in glioblastoma that may serve as a target for therapeutic intervention." (PMID 25955030, 2015). "While EGFR reportedly induces ANGPTL4 expression and promotes tumor angiogenesis in malignant gliomas, ANGPTL4 activation apparently is independent of EGFR upregulation in Mesenchymal glioblastoma xenografts." (PMID 25955030, 2015).
ischemia (6 papers, 2021 to 2025). A hypoperfusion of the BLOOD through an organ or tissue caused by a PATHOLOGIC CONSTRICTION or obstruction of its BLOOD VESSELS, or an absence of BLOOD CIRCULATION. "ANGPTL4 has also been associated with the regulation of inflammation and repair following MI and ischemia." (PMID 40723247, 2025). "The pathogenesis of many of these diseases are associated with inflammation, dysregulation of vascular permeability, angiogenesis, and ischemia, all of which are processes where ANGPTL4 is involved." (PMID 40723247, 2025). "This increase in serum ANGPTL4 level in patients with more severe ischemia reinforces the potential role of ANGPTL4 not only as a marker for AIS presence but also as an indicator of its severity." (PMID 39972951, 2025). "ANGPTL4 has been shown to promote vessel integrity, increasing angiogenesis and stabilization of endothelial cells following MI and ischemia." (PMID 40723247, 2025). "We found that endothelial markers (Angptl4), and pericyte marker (Cyp1b1, Emp1, S1pr3, Serping1, and Cxcl1) were upregulated in prolonged ischemia." (PMID 35154109, 2022). "ANGPTL4 (2.7 ± 0.5 ng/ml) reduces renal injury and proteinuria and promotes kidney vascularization in ischemia." (PMID 35646873, 2022). "ANGPTL4 reduces renal injury and proteinuria by binding to glomerular endothelial ανβ5 integrin and inactivating LPL activity and promotes angiogenesis in ischemia." (PMID 35646873, 2022).
Lymphadenopathy (6 papers, 2018 to 2025). Enlargement (swelling) of a lymph node. "Cis-pQTL MR via the relatively common ANGPTL4 p.E40 K variant was conducted at five different phenotypes that may be related to lymphadenopathy and malabsorptive states." (PMID 38895109, 2024). "It is not yet clear whether a larger sampling of individuals deficient in ANGPTL4 activity would reveal abdominal lymphadenopathy, or whether therapeutic antagonism of ANGPTL4 late in life will have similar effects in humans." (PMID 29899519, 2018). "Furthermore, several female monkeys treated with ANGPTL4-inactivating antibodies showed lymphadenopathy characterized by lipid accumulation in the mesenteric lymph nodes." (PMID 35667416, 2022).
osteoarthritis (6 papers, 2014 to 2026). A noninflammatory degenerative joint disease occurring chiefly in older persons, characterized by degeneration of the articular cartilage, hypertrophy of bone at the margins and changes in the synovial membrane. "Increased expression of ANGPTL4 in osteoarthritis has been reported, furthermore, matrix metallopeptidase (MMP) expression is induced by ANGPTL4 and played a role in cartilage matrix remodeling." (PMID 30049845, 2018). "We have also examined whether circulating levels of ANGPTL4 differ in RA patients compared with that in normal controls or patients with osteoarthritis (OA)." (PMID 25289668, 2014). "However, the mechanisms by which the Angptl4 causes the adverse effects of osteoarthritis has not been fully elucidated." (PMID 36071864, 2022).
psoriasis (6 papers, 2020 to 2025). An autoimmune condition characterized by red, well-delineated plaques with silvery scales that are usually on the extensor surfaces and scalp. "Though several studies have explored the mechanism of ANGPTL4 in various disease models, the underlying mechanism in psoriasis remains elusive." (PMID 35860030, 2022). "The appearance of CXCL12, CCL19, and ANGPTL4 in both directions indicates the positive feedback signaling between keratinocytes and myeloid cells, which likely amplifies the pathogenesis of the psoriasis." (PMID 39999288, 2025). "In our experiments, imiquimod (IMQ)-induced psoriasiform dermatitis in mice and human keratinocytes (HaCaT) cells were used to study the potential roles and mechanisms of ANGPTL4 in psoriasis." (PMID 35860030, 2022). "Psoriasiform dermatitis models in mice were induced by IMQ treatment to investigate the effect of ANGPTL4 on psoriasis in vivo." (PMID 35860030, 2022). "Together, these results verified that ANGPTL4 was upregulated in psoriasis, suggesting a potential role of ANGPTL4 in psoriasis pathogenesis." (PMID 35860030, 2022). "The western blot and qRT-PCR results showed an obviously increased expression of ANGPTL4 and inflammatory cytokines within the psoriasis-like skin lesions, demonstrating that ANGPTL4 was stimulated in a psoriasis-like inflammatory environment." (PMID 35860030, 2022). "Our results suggested the potential use of therapeutic approaches targeting ANGPTL4 in psoriasis treatment." (PMID 35860030, 2022). "This is the first study to report on the role of ANGPTL4 in patients with psoriasis, lichen planus and vitiligo." (PMID 36144281, 2022). "The present study found that ANGPTL4 was significantly upregulated in psoriasis patients and IMQ-induced psoriasiform dermatitis in mice." (PMID 35860030, 2022). "Analyzing the relationship between the protein and laboratory parameters, we found a positive correlation between ANGPTL4 concentration and fasting glucose, but only in patients with psoriasis, which is consistent with the available literature." (PMID 36144281, 2022). "Further in vivo experiments and studies are needed to confirm the clinical value of ANGPTL4 in psoriasis." (PMID 35860030, 2022). "Among these overlapped candidate hub genes in the turquoise module, we eventually selected ANGPTL4 to explore its possible role in psoriasis." (PMID 35860030, 2022). "Angiopoietin-like protein 4 (ANGPTL4) is highly expressed in the skin lesions of psoriasis patients, ANGPTL4 recombinant protein promotes psoriasis-like skin lesions in mice, and the knockout of ANGPTL4 inhibits keratinocyte growth and expresses cytokines such as IL-17, IL-6, and TNF-α." (PMID 37762693, 2023). "Furthermore, several proteins, such as KRT17, KRT17, TWEAK, PCSK9, and ANGPTL4, are highly expressed in psoriasis and tumors and are involved in the development of these two diseases, and knockdown of these proteins exhibits therapeutic effects." (PMID 37762693, 2023). "This study explored the regulation and potential impact of ANGPTL4 on psoriasis." (PMID 35860030, 2022). "All of these results drive us to believe that keratinocytes ANGPTL4 may play a significant role in psoriasis development." (PMID 35860030, 2022). "It suggests that ANGPTL4 might be related to inflammation in the pathophysiological mechanism of psoriasis." (PMID 35860030, 2022). "ANGPTL4 concentration was statistically significantly higher in patients with LP compared to the control group (p < 0.01); moreover, it was significantly higher than in patients with psoriasis and vitiligo (p < 0.001, p < 0.01, respectively)." (PMID 36144281, 2022). "In conclusion, we demonstrated that ANGPTL4 participates in the pathogenesis of psoriasis." (PMID 35860030, 2022). "We found ANGPTL4 could promote proliferation and significantly upregulate the levels of pro-inflammatory factors in psoriasis." (PMID 35860030, 2022).
psoriasis (continued). "It should be further investigated in the future whether ANGPTL4 could become a marker of liver complications in subjects with vitiligo and psoriasis." (PMID 36144281, 2022). "Therefore, we hypothesize that ANGPTL4 could participate in psoriasis via regulating the keratinocytes proliferation and the expression of inflammatory cytokines in the skin." (PMID 35860030, 2022). "It is still unclear whether ANGPTL4 contributes to the proliferation of epidermis in psoriasis." (PMID 35860030, 2022). "Our study suggests that ANGPTL4 may be a promising therapeutic target for psoriasis in the future." (PMID 35860030, 2022). "Therefore, ANGPTL4 may also be an important bridge between psoriasis and cardiovascular disease." (PMID 35860030, 2022). "There was a positive correlation between ANGPTL4 concentration and fasting glucose (R = 0.43) and AST activity (R = 0.39) in patients with psoriasis." (PMID 36144281, 2022). "However, the expression and regulatory mechanism of ANGPTL4 in psoriasis remain unclear." (PMID 35860030, 2022). "To clarify the expression and localization of ANGPTL4 in psoriasis, we then collected skin samples from psoriasis and non-psoriasis patients for immunohistochemistry and immunofluorescence staining." (PMID 35860030, 2022). "ANGPTL4 could promote keratinocyte proliferation and inflammatory response via ERK1/2 and STAT3 dependent signaling pathways in psoriasis." (PMID 35860030, 2022). "Moreover, there was a positive correlation between ANGPTL4 concentration and ALT activity in patients with vitiligo and AST activity in patients with psoriasis." (PMID 36144281, 2022). "The steeper combined reduction rate of PEDF, KLK-7, MDC, ANGPTL4 from Week 4 to 16 differentiated responders from non-responders in the psoriasis trial." (PMID 31953524, 2020). "More specifically, we identified PEDF, MDC and ANGPTL4 from the same pharmacodynamic pattern as IL-17A and KLK-7, for which the combined rate of decline between Week 4 and 16 could differentiate apremilast clinical responses in psoriasis." (PMID 31953524, 2020). "Furthermore, ANGPTL4 could promote keratinocyte proliferation and induce inflammatory response via ERK1/2 and STAT3 dependent signaling pathway, resulting in pathological changes in psoriasis." (PMID 35860030, 2022).
squamous cell carcinoma (6 papers, 2009 to 2025). A carcinoma arising from squamous epithelial cells. "Whether less vascularization and very low metastatic potential of BCC compared to squamous cell carcinomas could be related to high levels of ANGPTL4 requires further investigations." (PMID 19287498, 2009).
bladder cancer (5 papers, 2017 to 2025). "For instance, in bladder cancer, the ANGPTL4/SDC1 signaling axis mediates the interaction between tumor cells and plasma cells, leading to poor immune response." (PMID 40493409, 2025). "Taken together, ANGPTL4 might be one of the upstream regulators in DATS-mediated signaling cascades, and thus a prognostic marker for DATS-treated bladder cancer patients associated with muscle invasiveness." (PMID 28680385, 2017). "Thus, this study identified ANGPTL4 as a novel potential regulatory factor in the suppression of proliferation, migration, and invasion of DATS-treated bladder carcinoma EJ cells." (PMID 28680385, 2017).
cervical cancer (5 papers, 2021 to 2025). A primary or metastatic malignant neoplasm involving the cervix. "ANGPTL4 knockdown inhibits proliferation and promotes apoptosis in SiHa cervical cancer cells." (PMID 35178306, 2022). "Therefore, further study should be conducted to reveal the molecular mechanism by which FSCN1 regulates the expression of HBP1 and ANGPTL4 in cervical cancer." (PMID 35178306, 2022). "In addition, ANGPTL4 is overexpressed in cervical cancer, which predicts poor prognosis." (PMID 35178306, 2022). "Thus, FSCN1 negatively regulates four transcription factors (HLTF, HBP1, ZNF664, DDX17) and positively regulates ANGPTL4 (an angiogenic factor) and EPHA2 in both HeLa cells and cervical cancer tissues." (PMID 35178306, 2022).
dyslipidaemia (5 papers, 2018 to 2024). "APOC3, ANGPTL3, and ANGPTL4 are circulating proteins that are actively pursued as pharmacological targets to treat dyslipidaemia and reduce the risk of atherosclerotic cardiovascular disease." (PMID 38895109, 2024). "Angiopoietin-like 4 is also capable of inducing dyslipidaemia, which is another crucial feature of MCD." (PMID 40729293, 2024). "IH has also been shown to play an important role in inhibiting LPL activity and increasing ANGPTL4 levels, leading to dyslipidaemia." (PMID 30524367, 2018). "Our data show that ANGPTL4 level was increased in subjects with OSA, which highlights the potential role of ANGPTL4 in OSA and the associated complications, such as dyslipidaemia." (PMID 30524367, 2018). "In addition, therapies aimed at reducing plasma levels of ANGPTL4 may provide additional benefits to patients with dyslipidaemia and T2D." (PMID 38895109, 2024).
endothelial dysfunction (5 papers, 2020 to 2025). In vascular diseases, endothelial dysfunction is a systemic pathological state of the endothelium (the inner lining of blood vessels) and can be broadly defined as an imbalance between vasodilating and vasoconstricting substances produced by (or acting on) the endothelium. "As ANGPTL4 is implicated in vascular inflammation and endothelial dysfunction further investigations of ANGPTL4 function in adult IgAV are warranted." (PMID 38610060, 2024). "ANGPTL4 is a crucial biomarker in infectious diseases characterized by endothelial dysfunction and vascular permeability." (PMID 40006981, 2025). "Circulating ANGPTL3 and ANGPTL4 undergo variable changes in obese patients with different metabolic phenotypes; changes in ANGPTL4 relate to endothelial dysfunction, making this protein a possible target for vascular prevention in these patients." (PMID 34440242, 2021). "The interplay between DENV, endothelial dysfunction, and ANGPTL4 has gained attention recently." (PMID 40006981, 2025). "A more recent study examined endothelial cell biomarkers in a follow-up to the TRACER trial and reported increases in pro-inflammatory biomarkers such as angiopoietin-like 4 (ANGPTL4) in patients who received vorapaxar treatment, suggesting that vorapaxar causes endothelial dysfunction." (PMID 37176005, 2023). "ANGPTL4 actively contributes to endothelial pathogenesis, directly modulating critical functions by binding to VE-cadherin and claudin-5, regulating vascular permeability and angiogenic processes; it is not just a consequence of endothelial dysfunction." (PMID 40006981, 2025).
hemangioma (5 papers, 2019 to 2025). A benign vascular lesion characterized by the formation of capillary-sized or cavernous vascular channels. "Broader discussion of the role of ANGPTL4 in hemangiomas and other pathologies with a limited number of studies on the role of ANGPL4 have largely been left out of this review." (PMID 40723247, 2025). "The β-blocker propranolol is used to suppress aberrant ANGPTL4 expression in the treatment of hemangiomas." (PMID 36902020, 2023). "As opposed to its S- counterpart, R-propranolol does not exert beta-blocker activity but was shown to reduce the angiogenic factor ANGPTL4 (more efficiently) in hemangioma stem cells." (PMID 36902020, 2023). "Using immunohistochemistry, we demonstrated that ANGPTL4 is present in authentic hemangioma of infancy." (PMID 31701018, 2019). "Two recent studies have suggested that ANGPTL4 may play a role in hemangiomas, which are benign growths of extra blood vessels." (PMID 40723247, 2025). "Moreover, R-propranolol isomers downregulate VEGF and angiopoietin-like 4 (ANGPTL4) in hemangioma stem cells (HemSCs), thus inhibiting tumor growth." (PMID 39687294, 2024). "Finally, we provide the first description of a role of ANGPTL4 in the pathogenesis of hemangioma of infancy." (PMID 31701018, 2019). "R-propranolol was shown to reduce the pro-angiogenic factor ANGPTL4 in a murine hemangioma model, without having beta-blocker activity and thus circumventing the potential side effects that could be caused by the beta-blocker activity of S-propranolol." (PMID 36902020, 2023).